TNF (tumor necrosis factor)
Diseases named in the same sentence as TNF in open-access papers (continued):
Sharing a sentence is not in itself a finding about the gene and the disease.
keloid (39 papers, 2009 to 2026). An irregularly shaped, elevated mark on the skin caused by deposits of excessive amounts of collagen during wound healing. "The upregulated genes in the keloid Treg cells, compared to normal scar Treg cells, were associated with the TNF signaling pathway, IL-17 signaling pathway, and apoptosis." (PMID 39872534, 2024). "IL-6 and TNFα, which were upregulated by FnIII-1c in both skin fibroblast lines, have been implicated in the development of keloid and hypertrophic scars." (PMID 37228128, 2023). "Ogawa (2017) suggested that keloids and hypertrophic scars are derived from an abnormal inflammatory reaction in the skin since proinflammatory factors, including IL-1α, IL-1β, IL-6, and TNF-α, are associated with keloid formation." (PMID 33282860, 2020). "The increase of proinflammatory cytokines, such as TNF-α, IL-1 and IL-6, in keloid tissue, indicated that localized inflammatory response is present in patients with keloids." (PMID 41556665, 2026). "Pro-inflammatory cytokines like IL-6, TNF-α, and IL-1β sustain chronic inflammation in the keloid tissue, further stimulating fibroblast activity and collagen production." (PMID 40741005, 2025). "The expression of TNF‐α, IL‐1β, and IL‐6—key inflammatory cytokines involved in keloid formation—was measured, and the biocompatibility of CNDS@Simvastatin was evaluated to ascertain its impact on important organs." (PMID 39313951, 2025). "By inhibiting NF-κB activation, curcumin reduces the levels of cytokines such as IL-6 and TNF-α, decreasing inflammation and preventing fibroblast hyperproliferation in keloid tissue." (PMID 40741005, 2025). "Other metabolites, including quercetin and resveratrol, also exhibit anti-inflammatory effects by reducing IL-6 and TNF-α levels and decreasing inflammatory cell infiltration in keloid tissue." (PMID 40741005, 2025). "In conclusion, keloid and AD share some common inflammatory and immune pathways, including TNF signaling, Toll-like receptor signaling, Th17 cell differentiation, NF-κB signaling, cytokine-cytokine interaction, and chemokine signaling pathways." (PMID 38476235, 2024). "This is supported by the upregulation of pro-inflammatory cytokines such as interleukin (IL)-1α, IL-1β, IL-6, and tumour necrosis factor (TNF)-α in keloid tissues." (PMID 39119435, 2024). "The results showed that the gene profiles of keloid were mainly enriched in chemokine signaling, TNF signaling pathway, neutrophil chemotaxis, immune response, inflammatory response, immune-related pathways, etc." (PMID 38476235, 2024). "In the present study, the hub genes (CHI3L1, IL1RN, MMP7, TNFAIP3, and TNFAIP6) were mainly involved in the regulation of inflammatory response, IL-17 signalling pathway, and TNF signalling pathway, which is consistent with previous findings in keloids." (PMID 37685578, 2023). "The reticular dermis has been proposed as the main locale of chronic inflammation underscoring the formation of keloid scars with upregulation of various proinflammatory cytokines, including IL-1α, IL-1β, IL-6, and tumor necrosis factor (TNF)-α." (PMID 37033989, 2023). "It was also found to induce apoptosis of keloid fibroblasts and keratinocytes and to inhibit LPS-induced TNF-α production, as well as the migration of keloid fibroblasts." (PMID 37511889, 2023). "TNF-α promotes cell proliferation by activating the nuclear factor (NF)-κB, and several studies have shown that NF-κB participates in keloid formation." (PMID 37685578, 2023). "TNF-α-stimulated gene-6 (TSG-6), a protein suppressed in keloid fibroblasts, has been shown to attenuate IL-1β, IL-6, and TNF-α when intradermally injected into hypertrophic scars." (PMID 37033989, 2023). "Mast cell-derived chymase enhances angiotensin II expression, leading to local activation of the renin-angiotensin system and upregulation of TGF-β1, TNF-α, platelet-derived growth factor, and IL-1β in keloid fibroblasts." (PMID 37033989, 2023).
keloid (continued). "First, keloids express high levels of TNF-α and TGF-β and normal keratinocytes cultured with these cytokines causes them to gain a fibroblastic morphology, express the mesenchymal marker vimentin." (PMID 35743263, 2022). "To explore the effect of TNF‐α on GADD153 expression in keloid fibroblasts, we added different concentrations of TNF‐α to the cultured medium and incubated the solutions for 48 h." (PMID 34472704, 2021). "The effect of the exogenous administration of TNF‐α on GADD153 protein expression in keloid fibroblasts was dose dependent." (PMID 34472704, 2021). "The release of proinflammatory cytokines (interleukin (IL)-1, IL-6 and tumor necrosis factor (TNF)-α) in keloid tissues increases sensitivity to injury and upregulates these cytokines compared to the general population." (PMID 33413286, 2021). "One report identified up-regulation of the proinflammatory cytokines, IL-1α, IL-1β, IL-6, and TNFα, in keloid fibroblasts." (PMID 33329590, 2020). "Immunohistochemical staining showed IL-17, IL-1β, IL-6, and TNF-α level were increased in the perilesional area of keloids compared with normal tissue or the keloid intralesional area." (PMID 31814061, 2020). "Specifically, 15 genes downstream of NF-κB signaling were up-regulated in keloid fibroblasts compared to normal skin fibroblasts after TNF-α treatment." (PMID 33343575, 2020). "IL-1α, IL-1β and TNFα mRNA expression levels decreased in pathologic scars compared to healthy skin, especially IL-1β in keloid scars." (PMID 30765798, 2019). "In the keloids, the inflammatory reaction is strong, and the levels of pro-inflammatory cytokines, such as IL-1, IL-6, and tumour necrosis factor alpha (TNFα), are high." (PMID 31231509, 2019). "The development of keloids is accompanied by changes in inflammatory factors, such as interleukin (IL)-6, IL-1, IL-8 and tumour necrosis factor-α (TNF-α)." (PMID 28498357, 2017). "In the present study, we evaluated the percentages of total collagen and type I and type III collagens and the relative number of mRNA copies for TGF-β, IFN-γ, IFN-γR1, TNF-α, and IL-10 in keloid fragments compared to normal scars." (PMID 28638180, 2017). "Additionally, elevated levels of pro‐inflammatory cytokines such as IL‐1α, IL‐1β, IL‐6, and TNF‐α in keloids contribute to chronic inflammation by increasing fibroblast proliferation, inhibiting apoptosis, and driving ECM synthesis." (PMID 41049267, 2025). "Additionally, they suppress pro-inflammatory cytokine production (IL-6, TNF-α) via NF-κB pathway inhibition, reducing the inflammatory environment that promotes keloid growth." (PMID 40741005, 2025). "Moreover, the reduction of GRHL2 expression can affect the TGF-β, TNF-NFκB, and IL-6 signaling pathways of keratinocytes, thereby potentially influencing their interaction with the keloid microenvironment." (PMID 39402063, 2024). "Fourth, BTXA‐activated GADD153 protein expression in keloid fibroblasts via the TNF‐α pathway." (PMID 34472704, 2021). "Our results indicate that BTXA enhances the expression of TNF‐α in keloid fibroblasts." (PMID 34472704, 2021). "Previous research has also reported an increased gene expression of TNF‐α in keloid tissues." (PMID 34472704, 2021). "In addition, proinflammatory factors, for example interleukin (IL)-1α, IL-1β, IL-6, and tumor necrosis factor-α are overexpressed in keloid, which proposes that the gene expression of these factors in the skin are responsive to trauma." (PMID 32850775, 2020). "Moreover, proinflammatory factors, such as interleukin (IL)-1α, IL-1β, IL-6, and tumor necrosis factor-α are upregulated in keloid tissues, which suggests that, in patients with keloids, proinflammatory genes in the skin are sensitive to trauma." (PMID 28287424, 2017). "Moreover, keloids feature a persistently inflamed microenvironment, with sustained infiltration of macrophages, mast cells, and T lymphocytes, along with elevated pro‐inflammatory cytokines such as IL‐1β, IL‐6, and TNF‐α." (PMID 41049267, 2025).
keloid (continued). "In this study, the TNF signalling pathway was significantly activated in keloid recurrence tissues, suggesting that the TNF-alpha may be a target to prevent the recurrence of keloids." (PMID 37685578, 2023). "Thus, we found no studies on TNF-α associated with keloids and although this cytokine is important in the healing process, its role in keloid is not well elucidated." (PMID 28638180, 2017). "These cells participate in various aspects of immune regulation during the development of keloids, such as the release of inflammatory mediators (e.g., interferon-γ(IFN-γ), IL-2, IL-6, TNF-α, IL-6, IL-10), as well as cell proliferation and migration." (PMID 40718487, 2025). "Keloid memory T cells are less adept at producing TNF-α and more prone to generating IFN-γ resulting in exuberant but dysregulated T cell responses in keloids." (PMID 41007836, 2025). "Tumor necrosis factor (TNF), IL-6, and IFN-β are upregulated in keloids, promoting cell migration and proliferation." (PMID 41562114, 2025). "Curcumin has been shown to inhibit the production of inflammation-related cytokines such as tumor necrosis factor-α (TNF-α), interleukin-1β (IL-1β), and interleukin-6 (IL-6), all of which play pivotal roles in keloid formation." (PMID 38284901, 2024). "Additionally, keloid formation is closely related to inflammatory responses, especially inflammation-related factors, such as interleukin 6, transforming growth factor-β, and tumor necrosis factor-α and inflammation-related cells, such as neutrophils, mast cells, and lymphocytes." (PMID 35967426, 2022). "In vitro, the authors were able to show that the expression of IL-6 and TNF-α, as well as the production of α-SMA and collagen I, by human keloids fibroblast decreased after paclitaxel administration." (PMID 33343575, 2020). "In keloids, TGF-β upregulates the expression of anti-inflammatory cytokines like IL-10 while downregulating the levels of pro-inflammatory cytokines such as IL-6 and TNF-α, thus regulating the local immune microenvironment." (PMID 40718487, 2025). "In the context of keloids, the JAK-STAT pathway is activated by pro-inflammatory factors overexpressed in keloid tissues, such as IL-1β, IL-6, IL-17, and tumor necrosis factor (TNF)-α." (PMID 39201463, 2024). "In keloids, the mechanotransduction pathways may involve the transforming growth factor-β (TGF-β)/Smad, MAPK, integrin, RhoA/ROCK, Wnt/β-catenin, and TNF-α/nuclear factor kappa-light-chain-enhancer of activated B cells (NF-κB) pathways." (PMID 23634948, 2013). "With redox balance, TGF-β inhibits the production of pro-inflammatory cytokines such as TNF-α, IL-1β, and IL-6, stimulates IL-10, allows the differentiation of fibroblasts into myofibroblasts to help cover wounds, inhibits the TGF-β/Smad pathway and consequently reduces fibrosis and keloids." (PMID 39061892, 2024). "Significantly, the expression of mRNA for TGF-β in keloid was increased, the expressions of IFN-γ, IFN-γR1, and IL-10 were lower, and IFN-γR1 and TNF-α had no statistical difference." (PMID 28638180, 2017).
obstructive sleep apnea (39 papers, 2012 to 2025). "Although numerous studies have suggested the association between TNF-α-308G/A polymorphism and susceptibility to obstructive sleep apnea (OSA), the results remained controversial and ambiguous." (PMID 37595008, 2023). "It is shown that certain inflammatory parameters including CRP, fibrinogen, IL-6, and Tumor Necrosis Factor-α (TNF-α) are linked with higher cardiovascular risk in patients with obstructive sleep apnea." (PMID 35694268, 2022). "At a physiological level, OSA and OSAS (Obstructive Sleep Apnea Syndrome) are associated with intermittent hypoxemia, higher serum and plasma interleukin-6 levels, and higher serum and plasma TNF-alpha levels, always compared to healthy controls." (PMID 33919250, 2021). "The aim of our study was to investigate the association between the TNF-α-308G/A polymorphism and obstructive sleep apnea syndrome (OSAS)." (PMID 25192323, 2014). "TNF-α has been implicated in the sleepiness associated with obstructive sleep apnea." (PMID 26543719, 2015). "In this context, our study aimed to determine the potential utility of potential biomarkers, such as IL-6, IL-8, IL-10, TNF-α, CRP, and S100B, in the diagnostic process of obstructive sleep apnea (OSA)." (PMID 37762178, 2023). "In a recent meta-analysis, the values of TNF-α have been reported to vary from ≈0.4 to ≈300 pg/mL in healthy adults and from ≈0.1 to nearly 1000 pg/mL in adults suffering from Obstructive Sleep Apnea Syndrome (OSAS)." (PMID 36010524, 2022). "A negative correlation between circulating adropin and proinflammatory signals, such as TNFα or IL-6, was reported in patients with obstructive sleep apnea." (PMID 34199277, 2021). "In pediatric obstructive sleep apnea patients, TNFα levels increase, and are closely related to sleepiness." (PMID 33192676, 2020). "The cardiovascular complications that frequently accompany obstructive sleep apnea syndrome (OSAS) are thought to develop as a result of inflammatory stress associated with cytokines such as IL-6 and TNF-α." (PMID 24895539, 2014). "Patients with obstructive sleep apnea show significant increases in serum levels of TNF-α, IL-1β, and IL-6." (PMID 22578011, 2012). "It is noteworthy that two of these cytokines, IL-6 and TNF-alpha, are also elevated in the serum of individuals with obstructive sleep apnea and sleep deprivation and correlate with fatigue and sleepiness in general population studies." (PMID 23316361, 2012). "Other studies on obstructive sleep apnea syndrome suggested that patients with obstructive sleep apnea syndrome showed high serum levels of tumor necrosis factor-α (TNF-α), IL-6, CRP, and spontaneous production of IL-6 by monocytes compared with obese control subjects." (PMID 34589489, 2021). "At present, the improvement of TNF-α after continuous positive airway pressure (CPAP) treatment of obstructive sleep apnea-hypopnea syndrome (OSAHS) is still controversial." (PMID 36952521, 2023). "The purpose of this study is to explore the anti-inflammatory role of microRNAs (miR)-21 and miR-23 targeting the TLR/TNF-α pathway in response to chronic intermittent hypoxia with re-oxygenation (IHR) injury in patients with obstructive sleep apnea (OSA)." (PMID 32028672, 2020). "Tumor necrosis factor-α (TNF-α) has been reported to play a part in the development of obstructive sleep apnea (OSA) and its complications." (PMID 32787816, 2020). "Background and Objectives: Determination of the impact of obstructive sleep apnea (OSA) on the cognitive function, and serum tumor necrosis factor-α (TNF-α), interleukin (IL)-6 and 1β levels and the effect of OSA management on these variables in children." (PMID 36837406, 2023). "After the analysis of the levels of pro and anti-inflammatory markers (IL-1β, IL-4, IL-6, IL-8, IL-10, Il-15, TNF-α, CRP, α1-GP) in the tonsils, we observed higher levels of markers IL-8 and IL-10 in pediatric patients with obstructive sleep apnea syndrome." (PMID 30213594, 2020).
obstructive sleep apnea (continued). "Patients with obstructive sleep apnea had higher plasma, serum, and intracellular levels of TNF-α, while several studies emphasized the role of TNF-α in OSA-related cardiovascular morbidity." (PMID 35694268, 2022). "Verify the levels of the inflammatory markers, IL-1β, IL-4, IL-6, IL-8, IL-10, IL-15, TNF-α, CRP and α1-GP, in the tonsils of children with and without obstructive sleep apnea syndrome." (PMID 30213594, 2020).
Parkinson’s (39 papers, 2010 to 2025). "EPO administration could rescue the expression of TH in rats in which parkinsonism was induced with rotenone or 6-hydroxydopamine, together with decreased levels of tumor necrosis factor alpha in the same brain areas affected by PD." (PMID 33467745, 2021). "Studies in PD patients show evidence of augmented levels of potent pro-inflammatory molecules e.g., TNF-α, iNOS, IL-1β whereas in experimental Parkinsonism it has been consistently demonstrated that dopaminergic neurons are particularly vulnerable to activated glia releasing these toxic factors." (PMID 25883554, 2015).